GAB1 (GRB2 associated binding protein 1)
Diseases named in the same sentence as GAB1 in open-access papers (continued):
Sharing a sentence is not in itself a finding about the gene and the disease.
Sepsis (10 papers, 2020 to 2026). Sepsis is defined as life-threatening organ dysfunction caused by a dysregulated host response to infection. "Here, we report that Grb2-associated binder 1 (Gab1) expression is diminished in the intestines of both septic patients and established sepsis models." (PMID 41624377, 2026). "Epithelial Gab1 deficiency rendered mice susceptible to lipopolysaccharide (LPS)-induced sepsis by sensitizing IECs to apoptosis, thereby contributing to systemic inflammation and markedly exacerbating septic lethality." (PMID 41624377, 2026). "Additionally, in lung injury mediated by sepsis, lncRNA taurine up-regulated 1 (TUG1) guards against sepsis-caused ALI through the regulation of the miR-34b-5p/GRB2-associated binding protein 1 (GAB1) axis." (PMID 34592882, 2021). "Among those lncRNAs, TUG1 is reported to principally impair miR-34b-5p-mediated downregulation of GAB1, thereby restraining sepsis-triggered acute kidney injury." (PMID 34743197, 2021). "A previous study indicated the ability of TUG1 to impair miR-34b-5p-mediated down-regulation of GAB1, thereby exercising a preventive effect against sepsis-induced acute kidney injury." (PMID 34743197, 2021). "The induction of TUG1 ameliorated sepsis-induced lung injury, the secretion proinflammatory cytokines, and apoptosis via inhibiting miR-34b-5p and promoting GAB1." (PMID 32087725, 2020). "TUG1 alleviates sepsis-induced acute lung injury by targeting miR-34b-5p/GAB1." (PMID 34362467, 2021). "Finally, to ascertain TUG1 alleviated sepsis-induced ALI via targeting miR-34b-5pand GAB1, we co-transfected PMVECs with TUG1-expressing vector and miR-34b-5p mimics (or control mimics) before LPS stimulation." (PMID 32087725, 2020). "TUG1 alleviated sepsis-induced inflammation and apoptosis via targeting miR-34b-5p and GAB1." (PMID 32087725, 2020). "Moreover, in vitro data showed that the production of GAB1 was inversely regulated by miR-34b-5p, but was positively correlated with the expression of TUG1, suggesting the involvement of GAB1 in sepsis-induced ALI." (PMID 32087725, 2020). "In the present study, we reported that lncRNA TUG1 ameliorated sepsis-induced ALI by the suppression of inflammatory responses and apoptotic activity, via targeting miR-34b-5p and GAB1." (PMID 32087725, 2020). "Additionally, CASC9 and TUG1 alleviated the sepsis-induced ALI via affecting the miR-195-5p/PDK4 axis and miR-34b-5p/GAB1 axis." (PMID 34126975, 2021).
colorectal cancer (8 papers, 2017 to 2023). A primary or metastatic malignant neoplasm that affects the colon or rectum. "In hepatocellular and colorectal carcinomas, the association of reduced migratory and invasive capacity related to GAB1 deletion is attributed to microRNA-200A, microRNA-105, and microRNA-409-3p, respectively." (PMID 37627207, 2023). "It was associated with GAB1 in the tumor proliferation and metastasis of head and neck squamous cell carcinoma and colorectal cancer." (PMID 35903358, 2022). "Gab1 expression is associated with UC therapeutic outcomes and colorectal cancer." (PMID 36795486, 2023). "Furthermore, epithelial Gab1-deficient mice displayed aggravated colorectal cancer driven by chronic colitis." (PMID 36795486, 2023). "For example, miR-409-3p is known to regulate GAB1 in colorectal cancer, and we were able to further confirm the mechanistic link between miR-409-3p and another miRNA, miR-411-3p, with the regulation of GAB1 in our models." (PMID 37169950, 2023). "It has been also depicted that GAB1 leads to partial apoptosis induction in HCT116 colorectal cancer cells through miR-5582-5p modulation." (PMID 37627207, 2023). "GAB1 has been reported to be required for the stimulation of macrophage-mediated invasion in gastric carcinoma cell line CR-1739 and colorectal carcinoma cell line CRL-2577." (PMID 37627207, 2023). "Besides Gab2, Gab1 is also shown to be positively correlated with tumor proliferation and metastasis in head and neck squamous cell carcinoma and colorectal cancer." (PMID 30665442, 2019). "Collectively, our study defines a protective role for Gab1 in colitis and colitis-driven colorectal cancer by negatively regulating RIPK3-dependent necroptosis, which may serve as an important target to address necroptosis and intestinal inflammation–related disease." (PMID 36795486, 2023).
ovarian carcinoma (7 papers, 2010 to 2025). A malignant neoplasm originating from the surface ovarian epithelium. "We also found that ANGII treatment increased the phosphorylation of EGFR with activation of downstream Gab1 and Shc proteins in ovarian cancer cells." (PMID 30845964, 2019). "On the other hand, GAB1 recruitment and phosphorylation for activation of the SHP2-ERK pathway have been shown to be essential in enhancing FER-induced metastasis in ovarian cancer." (PMID 37627207, 2023). "It was reported that FER regulated GAB1 and MET phosphorylation and activated SHP2-ERK signaling in ovarian cancer." (PMID 34295819, 2021).
melanoma (6 papers, 2015 to 2024). A malignant, usually aggressive tumor composed of atypical, neoplastic melanocytes. "Downstream increases in ERK and AKT phosphorylation were also observed, suggesting that changes in total MET and GAB1 prime BRAF mutant melanoma cells for HGF-mediated rescue via downstream activation of the PI3K and MAPK signaling pathways." (PMID 28147313, 2017). "Using system pathway profiling analysis we reveal the molecular network model, which illustrates how different neurotrophin receptor-dependent adaptor proteins, including GRB2, SHC, and GAB1 connect activation of CD271 to the upregulation of AKT3 in CD271+ melanoma-initiating cells." (PMID 31118427, 2019). "Taken together these data suggest that the increases in total MET and GAB1 may prime BRAF mutant melanoma cells for HGF-mediated rescue." (PMID 28147313, 2017). "Another study has established that MAPK pathway inhibition following BRAF inhibitor treatment induced rapid increases in MET and GAB1 expression and MET amplification was also observed to co-exist with BRAF hotspot mutations and represent the most common amplification among RTKs in melanomas." (PMID 32659961, 2020). "Only MET and GAB1 exhibited significant induction following vemurafenib or PD0325901treatment, indicating this induction may contribute to the underlying mechanism of HGF rescue and explain the unique ability of HGF to rescue BRAF mutant melanoma cells from MAPK pathway inhibition." (PMID 28147313, 2017). "In addition, we showed that MAPK pathway inhibition induced rapid increases in MET and GAB1 levels, providing novel mechanistic insight into how BRAFV600E mutant melanoma is primed for HGF-mediated rescue." (PMID 28147313, 2017). "Besides Gab1, c-Met can also activate other molecules such as STAT3 which is involved in melanoma metastasis." (PMID 25971889, 2015). "In BRAFV600E mutant melanoma, where robust MAPK pathway signaling is present, we hypothesized that MET and GAB1 levels were repressed by an ERK-dependent negative feedback mechanism." (PMID 28147313, 2017).
atherosclerosis (5 papers, 2013 to 2025). A disease characterized by the build-up of fatty material and calcium deposition in the arterial wall resulting in partial or complete occlusion of the arterial lumen. "Taken together, these results suggested that loss of GAB1 is associated with atherosclerosis in ASO." (PMID 33584322, 2020). "But in ASO, little studies has showed a positive association between dysfunction of GAB1 and atherosclerosis." (PMID 33584322, 2020). "Taken together, our study first suggested that aberrant autophagy induced by loss of GAB1 is responsible for atherosclerosis at a late phase of the disease." (PMID 33584322, 2020). "Taken together, these findings show that endothelial Gab1 protects the endothelium from AngII-dependent vascular inflammation and atherosclerosis in the ApoE-null background, presumably in association with the downregulation of KLF2 and KLF4." (PMID 23431498, 2013). "Also, enhanced autophagy in Gab1-deficient vascular endothelial cells is observed in atherosclerosis." (PMID 36795486, 2023). "Given the importance of GAB1 in regulating autophagic signaling proteins, we questioned that how GAB1 is involved in the pathogenesis of atherosclerosis during ischemic stress." (PMID 33584322, 2020). "Functionally, we demonstrated that knockdown of GAB1 impaired cell proliferation, cell migration, and tube formation of HUVECs, which is believed to be a potential mechanism contributing to the development of atherosclerosis." (PMID 33584322, 2020). "Given the importance of GAB1 in the development of atherosclerosis, we further performed survival analysis to determine whether GAB1 expression is responsible for long-term survival of ASO patients." (PMID 33584322, 2020). "Therefore, our study aims to establish the relationship between GAB1 dysfunction and the onset of atherosclerosis." (PMID 33584322, 2020). "Targeting GAB1 may serve as a potential strategy for the atherosclerosis treatment." (PMID 33584322, 2020). "Further, Western blot analysis confirmed that the protein expression of GAB1 in intima of ASO popliteal arteries significantly decreased as compared with that of controls, suggesting that translation of GAB1 is destroyed upon atherosclerosis." (PMID 33584322, 2020). "By inhibiting the expression of Gab1, insulin-like growth factor 1 accelerates endothelial cells inflammation and atherosclerosis, suggesting that upregulation of miR-29a-3p in AOSD patients could facilitate inflammatory response by decreasing Gab1 expression." (PMID 30687316, 2018).
gastric cancer (5 papers, 2018 to 2025). A primary or metastatic malignant neoplasm involving the stomach. "Studies in the human gastric carcinoma cell line GTL‐16 cells demonstrated that prolonged HGF/SF‐MET signalling led to both multiubiquitination (proteasomal targeting) and K63‐linked polyubiquitination (lysosomal routing) of GAB1 in a CBL‐dependent manner." (PMID 40550626, 2025). "In gastric cancer tissues, Gαi1 immunoprecipitated with multiple RTKs (EGFR, PDGFRα and FGFR) as well as the adapter protein Gab1, mediating downstream Akt-mTOR activation." (PMID 38049415, 2023).
glioma (5 papers, 2017 to 2023). A benign or malignant brain and spinal cord tumor that arises from glial cells (astrocytes, oligodendrocytes, ependymal cells). "NLGN3 was found to induce Gab1 activation, indicated by increased phosphorylation at Tyr-627 and Tyr-307 39 in P1 primary human glioma cells and U251MG cells." (PMID 34373757, 2021). "A very recent study has suggested that Gab1 is important for activation of PI3K-Akt-mTOR activation in human glioma cells." (PMID 28291820, 2017). "Moreover, it has been found that microRNA-29a-3p downregulation induces GAB1 upregulation to promote glioma cell proliferation." (PMID 37627207, 2023). "Importantly, Gab1 silencing inhibited NLGN3-induced downstream signaling activation in glioma cells." (PMID 34373757, 2021). "In addition, decreased miR-29a-3p expression gives rise to enhanced proliferation of glioma cells via the upregulation of GAB1." (PMID 31892308, 2019). "A very recent study has explored expression of Gab1 in human glioma." (PMID 28291820, 2017). "Significantly, shRNA-mediated stable knockdown of Gab1 inhibited NLGN3-induced Akt, Erk1/2 and S6K phosphorylation in U251 and primary glioma cells." (PMID 34373757, 2021). "Transfection of two applied Gab3 siRNAs (“siGab3-a/-b”) efficiently downregulated Gab3 mRNA (but not Gab1) in the primary glioma cells." (PMID 28291820, 2017). "Here in glioma cells, Gαi1/3 silencing, by targeted shRNAs, blocked NLGN3-induced RTKs endosomal translocation and subsequent Gab1 activation, without affecting RTK phosphorylation and expression." (PMID 34373757, 2021).
viral infection (5 papers, 2015 to 2025). "Acute viral infection in humanized liver mice significantly decreased the level of hepatocyte p-Gab1." (PMID 38935609, 2024). "Consistent with an important role in the host innate immune response to viral infections, Gab1 is required for vesicular stomatitis virus (VSV) infection-induced IFN-alpha/beta production." (PMID 35083168, 2021). "GAB1 protein levels were elevated in cells infected with a virus lacking miR-US5-2 compared to cells infected with WT virus, indicating that GAB1 is a target of HCMV during viral infection." (PMID 32759334, 2020). "At 4 days postinfection, UL138 expression was increased in cells infected with the ΔmiR-US5-2 mutant virus, but was reduced in cells infected with the ΔmiR-US5-2/GAB1shRNA virus, indicating that through targeting GAB1, miR-US5-2 modulates UL138 expression during viral infection." (PMID 32759334, 2020). "Virus infection induced phosphorylation of focal adhesion kinase (FAK) but not Gab1, and blockage of FAK phosphorylation suppressed Akt phosphorylation." (PMID 26388843, 2015). "The downregulation of GAB1 reduces PI3K/Akt activity, which may promote viral infection." (PMID 40431739, 2025).
colon carcinoma (4 papers, 2013 to 2023). "In CRC, we found that the abundance of Peptostreptococcaceae is negatively associated with the expression of GAB1, a host gene for which overexpression stimulates tumour growth in colon cancer cells." (PMID 35577971, 2022). "Gab1 is also required for cellular differentiation in Caco-2 colon carcinoma." (PMID 24312291, 2013).
hilar cholangiocarcinoma (4 papers, 2013 to 2023). A cholangiocarcinoma that arises from the junction, or adjacent to the junction, of the right and left hepatic ducts. "GAB1 downregulation inhibits proliferation in hilar cholangiocarcinoma cell lines by decreasing PI3K/AKT signaling pathway activation." (PMID 37627207, 2023). "It has been reported that GAB1 controls the autocrine secretion of VEGF in hilar cholangiocarcinoma tumor cells, promoting angiogenesis and tumor invasion." (PMID 37627207, 2023). "GAB1 suppression increased apoptosis in hilar cholangiocarcinoma, chondrosarcoma cell lines by modulating the B-cell lymphoma 2 (BCL-2)/ Bcl-2 Associated X-protein (BAX) axis, and pancreatic carcinoma through microRNA-383 regulation." (PMID 37627207, 2023). "Suppression of GAB1 expression leads to G1 arrest in hilar cholangiocarcinoma and chondrosarcoma cell lines." (PMID 37627207, 2023). "In intrahepatic cholangiocarcinoma and hilar cholangiocarcinoma, GAB1 has been reported to promote cell proliferation and invasion and to decrease apoptosis." (PMID 26871477, 2016). "We believe that Gab1 likely regulate the malignant biological behaviors (e.g., growth, apoptosis and invasion) of hilar cholangiocarcinoma via the PI3K/Akt signaling pathway." (PMID 24312291, 2013). "Changes in PI3K/Akt pathway activity in hilar cholangiocarcinoma tumor cells after down-regulation of Gab1 and VEGFR-2 were also determined." (PMID 24312291, 2013). "Using immunohistochemical analysis, we detected high expression of Gab1 in hilar cholangiocarcinoma tissues and further confirmed that Gab1 was correlated with differentiation and lymphatic metastasis in patients by combining other clinical information." (PMID 24312291, 2013). "By analyzing 49 hilar cholangiocarcinoma cases, we find that the adapter protein Gab1 is closely related with the occurrence, invasion and metastasis of hilar cholangiocarcinoma." (PMID 24312291, 2013). "Gab1 regulates growth, apoptosis and invasion through the VEGFR-2/Gab1/PI3K/Akt signaling pathway in hilar cholangiocarcinoma cells and influences the invasion of tumor cells via MMP-9." (PMID 24312291, 2013). "We further investigated the signaling pathways that Gab1 was involved in and the effects of Gab1 on the biological behaviors of hilar cholangiocarcinoma using ICBD-1 cells." (PMID 24312291, 2013). "In addition, it has been previously reported that Gab1 regulates tumor cell growth, apoptosis and invasion through the VEGFR-2/Gab1/PI3K/Akt signaling in hilar cholangiocarcinoma cells." (PMID 30665442, 2019). "Finally, we detected MMP-9 levels in hilar cholangiocarcinoma tumor cells after down-regulation of Gab1 and VEGFR-2." (PMID 24312291, 2013). "Thus, we suspected a close relationship between high Gab1 expression and malignant biological behaviors (e.g., invasion and metastasis) of hilar cholangiocarcinoma." (PMID 24312291, 2013). "Because VEGFR-2 is an upstream protein of Gab1 in endothelial cells and VEGFR-2 and Gab1 were positively correlated in hilar cholangiocarcinoma, we examined the relationship between them in ICBD-1 cells and demonstrated that VEGFR-2 could regulate the activity of Gab1 in ICBD-1 cells." (PMID 24312291, 2013). "Correlation between Gab1 and VEGFR-2, Gab1 and MMP-9, and VEGFR-2 and MMP-9 expression in hilar cholangiocarcinoma tissues." (PMID 24312291, 2013). "OD analysis of VEGFR-2, Gab1 and MMP-9 expression in hilar cholangiocarcinoma tissues and biliary duct tissues with chronic inflammation." (PMID 24312291, 2013). "Evaluation of hilar cholangiocarcinoma specimens showed that VEGFR-2, Gab1 and MMP-9 were all closely correlated with hilar cholangiocarcinoma and its malignant biological behaviors and were related to each other." (PMID 24312291, 2013).